BMP7 (bone morphogenetic protein 7)
Diseases named in the same sentence as BMP7 in open-access papers (continued):
Sharing a sentence is not in itself a finding about the gene and the disease.
osteosarcoma (9 papers, 2011 to 2023). A usually aggressive malignant bone-forming mesenchymal neoplasm, predominantly affecting adolescents and young adults. "miR-542-3p often serves as a tumor suppressor in various cancers including epithelial ovarian cancer, hepatocellular carcinoma, osteosarcoma, and meanwhile, miR-542-3p promotes hepatic stellate cell activation and fibrosis by regulating BMP‐7." (PMID 31949464, 2019). "We showed that miR-21-5p and BMP-7 could be relevant markers of osteosarcoma cell lines." (PMID 36139691, 2022). "Further research showed that Transmembrane protein 119 (TMEM119) promoted osteosarcoma cell proliferation, migration, and invasion via increasing the TGF‐β pathway‐related factors (BMP2, BMP7, and TGF‐β) expression." (PMID 36408691, 2023). "However, our study showed that BMP-7 could be considered an osteosarcoma-specific marker." (PMID 36139691, 2022). "Evaluated osteosarcoma cell lines showed characteristic phenotypes with unique patterns related to upregulation of MMP-7, MMP-14, BMP-7, miR-21-5p, miR-124-3p and downregulation of lncRNA MEG3." (PMID 36139691, 2022). "Previous studies showed that BMP-7 and BMP-8 are overexpressed in osteosarcoma tissues, pointing to the importance of those molecules in tumour development." (PMID 36139691, 2022). "For instance, recombinant human (rh) BMP-7 exerted antineoplastic effects in HNSCC and rhBMP-2 was applied to treat osteosarcoma by increasing caspase-3 and Bax-mediated cell apoptosis in cancer." (PMID 27661009, 2016). "Previous data have shown that BMP-7 was highly expressed in human osteosarcoma cell lines but was not expressed in normal osteoblast samples." (PMID 25390068, 2014).
Peritoneal Fibrosis (9 papers, 2017 to 2025). Disorder characterized by a wide range of structural changes in PERITONEUM, resulting from fibrogenic or inflammatory processes. "Our study suggests a role for the TGFβ1/BMP7/Gremlin1/Smad pathway in peritoneal fibrosis with potential therapeutic implications." (PMID 34721005, 2021). "Together, these findings suggest that SSD can effectively inhibit peritoneal fibrosis, likely in a TGFβ1/BMP7/Gremlin1/Smad pathway dependent manner." (PMID 34721005, 2021). "This study aimed to investigate the regulatory effect of Saikosaponin d (SSD), a monomer extracted from the plant Bupleurum, on peritoneal fibrosis and the contribution of TGFβ1/BMP7/Gremlin1 pathway cross-talk in this process." (PMID 34721005, 2021). "One possibility is that Gremlin1 can activate the TGFβ pathway and inhibit the expression of BMP7 and Smad1/5/8, thereby inducing peritoneal fibrosis." (PMID 34721005, 2021). "Intraperitoneal administration of adenoviral vectors expressing bone morphogenetic protein-7 (BMP-7), which is an anti-fibrotic molecule, was also shown to ameliorate peritoneal fibrosis in a rat model." (PMID 30410706, 2017). "Similar to our findings, Io and colleagues demonstrated that the HDACi SAHA induced a higher expression of BMP-7 and prevented the peritoneal fibrosis induced by GC mice." (PMID 28873458, 2017). "Besides, Smad3 inhibition in uremic-PD rat models treated with recombinant BMP7 decreased peritoneal fibrosis, sub-mesothelial capillary density, and increased UF capacity." (PMID 35563220, 2022). "It remains unknown whether BMP7 and Gremlin are expressed in peritoneal tissue, and whether the BMP7/Smad1/5/8 pathway in involved in peritoneal fibrosis." (PMID 34721005, 2021). "Overall, our results suggest that the TGFβ1/BMP7/Gremlin1/Smad pathway may be a potential therapeutic target for peritoneal fibrosis." (PMID 34721005, 2021). "In particular, our study has also demonstrated that the monomer SSD may be able to reverse peritoneal fibrosis by regulating TGFβ1/BMP7/Gremlin1/Smad pathway." (PMID 34721005, 2021). "We then wondered whether the TGFβ1/BMP7/Gremlin1 pathway was involved in the progress of peritoneal fibrosis." (PMID 34721005, 2021). "Finally, our results also suggest that the monomer SSD may be able to reverse peritoneal fibrosis via regulation of the TGFβ1/BMP7/Gremlin1/Smad pathway." (PMID 34721005, 2021). "However, it remains to be seen whether cross-talk between the TGFβ/BMP7/Gremlin pathways occurs during the course of peritoneal fibrosis." (PMID 34721005, 2021). "The authors report a possible mechanism, Gremlin-1 enhances the TGF-β1 signalling and suppresses the expression of BMP7 and Smad1/5/8, leading to EMT and peritoneal fibrosis." (PMID 40918510, 2025). "On the other side, BMP-7 exerts antagonistic effects on TGF-β as in PD fluid-instilled rats and co-administration of BMP-7 ameliorated peritoneal fibrosis and increased capillary density." (PMID 35563220, 2022). "In fact, some studies showed that recombinant BMP‐7 (rBMP‐7) or adenovirus‐mediated expression of BMP‐7 reversed the TGF‐β1‐induced EMT and peritoneal fibrosis in in vitro or in vivo models." (PMID 33079436, 2020).
hepatocellular carcinoma (8 papers, 2012 to 2024). A malignant tumor that arises from hepatocytes. "In human hepatoma and renal cell lines BMP7 exposure increased SMAD6 levels, which reduced SMAD2/3-SMAD4 heteromerization." (PMID 34608249, 2021). "Whereas BMP4 and BMP7 were up-regulated in cirrhosis, BMP4 and BMP7 along with SRC were further up-regulated in hepatocellular carcinoma." (PMID 23991421, 2013). "Taken together, these results show that BMP7 mediates KDM5C-induced migration and invasion in hepatocellular carcinoma cells." (PMID 26503415, 2015).
chondrosarcoma (7 papers, 2012 to 2020). A malignant cartilaginous matrix-producing mesenchymal neoplasm arising from the bone and soft tissue. "BMP-7 upregulates integrin avb3 expression, thereby inducing the migration activity in human chondrosarcoma cells." (PMID 27661009, 2016). "In chondrosarcoma cells, BMP-7 enhances αvβ3 integrin expression through the c-Src/PI3K/Akt/IKK/NF-κB signaling pathway." (PMID 27929432, 2016). "Taken together, these data suggest that activation of c-Src, PI3K, Akt, and IKK are required for BMP-7-induced NF-κB activation in human chondrosarcoma cells." (PMID 25390068, 2014). "Previous reports have indicated that TGF-β and BMP-2, both highly homologous to BMP-7, are able to enhance cell motility and αvβ3 integrin expression in human chondrosarcoma cells, via pathways involving PI3K, Akt, and NF-κB." (PMID 25390068, 2014). "In conclusion, we have explored the signaling mechanisms of BMP-7 in the regulation of αvβ3 integrin expression in human chondrosarcoma cells." (PMID 25390068, 2014). "We have thus determined the role of the c-Src, PI3K/Akt, and NF-κB pathways in BMP-7-induced cellular motility in chondrosarcoma cells, especially at the level of integrin expression." (PMID 25390068, 2014). "Cells pretreated with the NF-κB inhibitors attenuated BMP-7-induced migration capability of chondrosarcoma cells." (PMID 25390068, 2014). "In the present study, we explored the molecular mechanism by which BMP-7 signaling to regulate cell motility in human chondrosarcoma cells." (PMID 25390068, 2014). "In addition, inhibition of the YAP/TAZ-activating kinases SRC and RAC was reported to interfere with the migratory and invasive properties of chondrosarcoma cells, while BMP-7-induced SRC activation promoted chondrosarcoma cell migration." (PMID 32326412, 2020). "We initially assessed the effects of BMP-7 on the migration activity in human chondrosarcoma cells." (PMID 25390068, 2014). "However, BMP-7 regulation in metastatic behavior and detailed mechanisms are still unclear in chondrosarcoma." (PMID 25390068, 2014). "In addition, another study also found that BMP-7 levels are higher in the high-grade chondrosarcoma than in the low-grade one." (PMID 25390068, 2014). "In this study, we characterized the effect of BMP-7 on the expression of αvβ3 integrin in human chondrosarcoma cells (JJ012), which may mediate and promote the cell motility." (PMID 25390068, 2014). "Taken together, these data suggest that c-Src activation may be involved in BMP-7-induced expression of integrin αvβ3 to enhance migration in human chondrosarcoma cells." (PMID 25390068, 2014). "However, there is little knowledge of the role of BMP-7 and its cellular function in chondrosarcoma cells." (PMID 25390068, 2014). "Therefore, we sought to determine whether the PI3K-Akt pathway is activated and involved in BMP-7-mediated increase of integrin αvβ3 expression and cell migration in human chondrosarcoma cells." (PMID 25390068, 2014). "Another chondrosarcoma cell line, SW1353 cells, was also observed that BMP-7 is able to induce αvβ3 integrin expression and enhance cell migration via the same pathway." (PMID 25390068, 2014). "Bone morphogenic protein 7 (BMP-7) is a cytokine that belongs to the TGF-β superfamily and was shown to induce invasion in hepatocellular carcinoma cells, breast cancer cells and chondrosarcoma cells." (PMID 27929432, 2016). "A previous study has shown that BMP-7 is significantly higher expressed in chondrosarcoma, while it is not detected or found at very low expression levels in normal cartilage samples." (PMID 25390068, 2014). "Although the roles of BMP-7 have emerged as an important factor in the regulation of cell motility across diverse cancer, the influence of BMP-7 on the motility of chondrosarcoma cells still remains largely unknown." (PMID 25390068, 2014). "Compared to normal cartilage, chondrosarcoma showed altered expression levels for BMP2 and BMP7." (PMID 23088614, 2012).
chondrosarcoma (continued). "Similarly, exogenous BMP-7 activates the c-Src/PI3K/AKT/IKK/NF-κB signaling pathway, thus resulting in the trans-activation of avβ3 integrin expression, which promotes tumor progression in human chondrosarcoma cells." (PMID 27661009, 2016). "However, the function of BMP-7 on chondrosarcoma cells has not yet been investigated." (PMID 25390068, 2014).
disc degeneration (7 papers, 2011 to 2025). "A wide array of existing studies have also confirmed that BMP7 mitigates disc degeneration in rabbit models of disc degeneration by increasing disc height and proteoglycan content." (PMID 36858954, 2023). "Based on statements of researchers in reviews from 2008 and 2011, a multicenter clinical trial in the United States was started, in which BMP-7 was intradiscally injected into human patients with degenerative disc disease." (PMID 26013758, 2015). "Intradiscal administration of recombinant human BMP-7 in a rabbit model of disc degeneration led to an increased disc height and enhanced proteoglycan content of the NP, showing its potential to promote repair in disc degeneration." (PMID 30157962, 2018). "On the contrary, the secreted BMP-7 also could stimulate BMDMSCs to transform into disc-like cells, to maintain the disc content, to prevent further disc degeneration." (PMID 26805824, 2016). "Moreover, there is existing evidence indicating that BMP7 is poorly-expressed in IDD, whereas over-expression of BMP7 can effectively treat disc degeneration by promoting regeneration of IVD." (PMID 36858954, 2023). "Baculo-BMP-7-BMDMSC can slow down the progression of disc degeneration, but could not provide evidence of regeneration." (PMID 26805824, 2016). "In conclusion, Baculo-BMP-7-BMDMSC can slow down the progression of disc degeneration, but could not provide evidence of regeneration." (PMID 26805824, 2016).
ischemia (7 papers, 2009 to 2025). A hypoperfusion of the BLOOD through an organ or tissue caused by a PATHOLOGIC CONSTRICTION or obstruction of its BLOOD VESSELS, or an absence of BLOOD CIRCULATION. "Kidneys damaged by ischemia have the potential to regenerate via a mechanism involving intrarenal induction of protective factors, including bone morphogenetic protein-7 (BMP7)." (PMID 40833473, 2025). "Our work extends this finding, demonstrating that BMP7 reduces apoptotic cell death in vivo as rAAV expression of BMP7 significantly decreased the number of TUNEL-positive cells in the periphery of the ischemia." (PMID 24618040, 2014). "Taken together, these data suggest that exogenously delivered BMP-7 has beneficial effects against ischemia." (PMID 24287916, 2013). "Pretreatment with BMP-7 prior to general hypoxia or ischemia reduced brain infarction volume and mortality in rats." (PMID 24287916, 2013). "It has been shown that treatment with exogenous BMP7 prior to induction of ischemia-induced injury or focal stroke leads to reduction in cerebral infraction and promotes functional recovery." (PMID 22701694, 2012). "BMP7 has neuroprotective capacity as it can enhance dendritic growth and protect cultured neurons from oxidative stress as well as reduce ischemia- or neurotoxin-mediated neurodegeneration in vivo via anti-apoptotic mechanisms." (PMID 23236355, 2012).
Cirrhosis (6 papers, 2012 to 2024). A chronic disorder of the liver in which liver tissue becomes scarred and is partially replaced by regenerative nodules and fibrotic tissue resulting in loss of liver function. "Protein expression of BMP-4 and BMP-7 was upregulated in HBV-related human cirrhosis/HCC samples, and the overexpression of BMP-4 and BMP-7 increased cell viability and enhanced cell migration in HCC cell-lines." (PMID 32050622, 2020). "In the same work, authors demonstrated that BMP4 and BMP7 were upregulated in patients with cirrhosis, HCC and cholangiocarcinoma and the increase correlated with the progression of cancer." (PMID 29295498, 2017). "However, BMP-7 mRNA correlated significantly with the levels of ductular reactions (r = 0.576, p = 0.031) in the cirrhosis group." (PMID 22839096, 2012). "However, it did positively correlate with BMP-7 levels in the cirrhosis group (r = 0.602, p = 0.023)." (PMID 22839096, 2012). "In the development of cirrhosis, miR-22 was shown to play a positive role by binding to the 3′-UTR to downregulate BMP7 expression." (PMID 29142236, 2017).
glomerulosclerosis (6 papers, 2011 to 2022). A hardening of the kidney glomerulus caused by scarring of the blood vessels. "BMP-7 ameliorates DKD by preventing glomerulosclerosis reversing diabetic kidney hypertrophy and restoring glomerular filtration rate (GFR) in the progression of DKD." (PMID 35314669, 2022). "Exogenous and overexpression of BMP-7 has been shown to improve renal function and prevent glomerular sclerosis in diabetic rats." (PMID 22474533, 2012). "Exogenous BMP-7 is mentioned to improve renal function and prevent glomerular sclerosis in diabetic rats." (PMID 21876712, 2011). "Besides exogenously supplemented BMP-7, transgenic overexpression of BMP-7 in FVB/N mice induced with STZ led to reduced podocyte dropout, glomerulosclerosis and interstitial collagen accumulation." (PMID 25954203, 2015).
Infertility (6 papers, 2016 to 2023). "In mice, BMP7 was involved in sertoli cell proliferation during early postnatal development, and BMP7 gene knockout mice caused infertility." (PMID 32982790, 2020). "However, it is possible to speculate and present a common mechanism whereby high expression of BMP7 in EUE in patients with endometriosis may be one of the causes of infertility in these women due to endometrial receptivity disorder." (PMID 37047609, 2023). "In mice, BMP7 was related to the proliferation of sertoli cells, and BMP7 knockout mice were infertile." (PMID 37372307, 2023). "BMP7 and phosphorylation of Smad5 were also detected, and the recovery of infertility function in treated mice was evaluated." (PMID 33736694, 2021).
Ureteral obstruction (6 papers, 2013 to 2022). Obstruction of the flow of urine through the ureter. "Smad1 mediated the BMP7-Alk3 signaling pathway to antagonize epithelial–mesenchymal transition and favor mesenchymal–epithelial transition in unilateral ureteral obstruction, which is a well-established model of severe renal interstitial injury and fibrosis." (PMID 27703192, 2016). "Febuxostat also exhibited a protective role in AKI experimental model through activation of BMP-7 signaling and inhibition of USAG-1 expression in unilateral ureteral obstruction (UUO) rats." (PMID 29340054, 2017).
B-cell lymphoma (5 papers, 2012 to 2024). "In another cohort of B‐cell lymphoma patients, BMP7 or ID3 high also significantly associated with better survival." (PMID 38229201, 2024). "Mino expressed ALK5 and was highly sensitive to BMP-7-induced apoptosis, in contrast to other B-cell lymphoma cell lines." (PMID 28489883, 2017). "Tonsillar B cells from all donors had detectable BMP7 mRNA, although at lower levels than the B-cell lymphoma cell line Sudhl-6." (PMID 28489883, 2017). "TGF-β-induced apoptosis is mediated via binding to ALK5, and BMP-7 showed similar signaling pattern to TGF-β in the B-cell lymphoma cell line Mino with phosphorylation of both Smad 1/5 and Smad 2/3, although at lower levels." (PMID 28489883, 2017). "Our data are in agreement with this as BMP-7 greatly increased the level of active caspase-3 in the B-cell lymphoma line Mino." (PMID 28489883, 2017). "As malignant B cells expressed BMP6 and BMP7, we next studied the effects of exogenously added BMPs in different B-cell lymphoma cell lines." (PMID 23049692, 2012). "Second, PRC2 represses the expression of BMP6, BMP7, and ACVR1 by H3K27me3 in B cell lymphoma in vitro and in vivo." (PMID 38229201, 2024). "Altogether, B-cell lymphoma cell lines had variable sensitivity to BMP-2-, -4- and -6-induced growth inhibition, but they were all resistant to BMP-7." (PMID 23049692, 2012). "Finally, the high levels of BMP6, BMP7, and ACVR1 correlate with a favorable survival outcome in B‐cell lymphoma patients." (PMID 38229201, 2024). "Although BMP7 induce apoptosis in normal B-cells, B-cell lymphoma cells can escape BMP-induced inhibition of cell growth suggesting an autocrine growth regulation and that malignant cells can escape autocrine growth inhibitory effect of BMP7." (PMID 24069261, 2013). "We focused on major types of B-cell lymphoma (BL, DLBCL ABC, DLBCL GCB, FL and PMBL) and demonstrated that the gene promoters of LRP12 (94%), CDH1 (92%), and BMPER (58%) were methylated at a high frequency, whereas DUSP4 and BMP7 showed lower methylation frequencies (32% and 22%, respectively)." (PMID 25226156, 2014).
Cerebral ischemia (5 papers, 2013 to 2023). Restriction of arterial blood supply to the brain associated with insufficient oxygenation to support the metabolic requirements of the tissue. "BMP7 has been reported to reduce ischemia-induced injury in the adult cerebral cortex, and reduce cerebral ischemia/reperfusion injury by attenuating oxidative stress and inhibiting neuronal apoptosis." (PMID 37875834, 2023). "Our screen experiment showed that most BMP family members, including BMP2, BMP4, BMP5, and BMP7 increased transiently at 24 h after brain ischemia." (PMID 34904361, 2022). "A number of TGFβ superfamily members are neuroprotective, such as BMP7 in cerebral ischemia and GDF5 in Parkinson's disease." (PMID 24586579, 2014). "BMP-7 significantly improved neurological and histological deficits, reduced the infarct volume, and decreased apoptotic cells after cerebral ischemia." (PMID 24287916, 2013). "Previous studies have indicated that bone morphogenetic protein-7 (BMP-7) is neuroprotective against cerebral ischemia/reperfusion (IR) injury." (PMID 24287916, 2013). "BMP7 has shown a protective effect against cerebral ischemia/reperfusion injury in rats, and its neuroprotective effect may be related to reducing oxidative stress and inhibiting neuronal apoptosis." (PMID 37875834, 2023). "Our results indicate that rAAV-induced neuronal overexpression of BMP7 is protective in MCAO and that rAAV-mediated polycistronic gene transfer can be applied to study cerebral ischemia in vivo." (PMID 24618040, 2014).